NETO2 (neuropilin and tolloid like 2)
Description:
Accessory subunit of neuronal kainate-sensitive glutamate receptors, GRIK2 and GRIK3. Increases kainate-receptor channel activity, slowing the decay kinetics of the receptors, without affecting their expression at the cell surface, and increasing the open probability of the receptor channels. Modulates the agonist sensitivity of kainate receptors. Slows the decay of kainate receptor-mediated excitatory postsynaptic currents (EPSCs), thus directly influencing synaptic transmission (By similarity).
Synonyms: BTCL2; FLJ10430; NEOT2
Tractability: Antibody: UniProt predicts a signal peptide or a membrane-spanning region. PROTAC: ubiquitination databases record sites on it; its protein half-life has been measured.
Gene: Protein-coding gene on chromosome 16 (47,077,703 to 47,144,006, reverse strand). Ensembl gene ENSG00000171208.
Subcellular location: Membrane
Subcellular location (Human Protein Atlas): Golgi apparatus
Gene Ontology:
Molecular function: ionotropic glutamate receptor binding
Biological process: neurotransmitter receptor localization to postsynaptic specialization membrane; regulation of neurotransmitter receptor localization to postsynaptic specialization membrane
Cellular component: postsynaptic density membrane; glutamatergic synapse; membrane; postsynaptic density; synapse
Genetic constraint (gnomAD): Loss-of-function variants: 22 observed, 50.14 expected, observed/expected ratio (o/e) 0.44, 90% interval 0.31 to 0.63. The upper end of that interval is the gene's LOEUF score, 0.63, which puts it in group 2 of 6, group 1 being the genes least tolerant of losing a copy. Missense variants: 507 observed, 614.34 expected, observed/expected ratio (o/e) 0.83, 90% interval 0.77 to 0.89. Synonymous variants: 197 observed, 210.38 expected, observed/expected ratio (o/e) 0.94, 90% interval 0.83 to 1.05.
Homologues: Orthologues: chimpanzee NETO2 (100% identical), macaque NETO2 (99% identical), dog NETO2 (98% identical), pig NETO2 (98% identical), rabbit NETO2 (98% identical), rat Neto2 (97% identical), guinea pig NETO2 (97% identical), mouse Neto2 (95% identical), tropical clawed frog neto2 (89% identical), zebrafish NETO2 (72% identical), zebrafish neto2b (58% identical). Paralogues in human: NETO1 (56% identical), DCBLD2 (21% identical), CUBN (19% identical), CNTNAP5 (18% identical), CNTNAP2 (18% identical), CNTNAP4 (17% identical), CNTNAP3 (15% identical), CNTNAP3B (15% identical), CNTNAP1 (15% identical), HEPHL1 (14% identical), NRXN2 (14% identical), NRXN3 (14% identical), and 23 more.
Diseases named in the same sentence as NETO2 in open-access papers:
NETO2 is named in the same sentence as 33 diseases in open-access papers, as found by Europe PMC text mining. Sharing a sentence is not in itself a finding about the gene and the disease. The quoted sentences say what the papers report.
colorectal cancer (10 papers, 2015 to 2024). A primary or metastatic malignant neoplasm that affects the colon or rectum. "Nevertheless, a study evaluating Chinese patients with colorectal cancer has revealed the upregulation of NETO2 in 52.6% of cases, reporting an association between expression and advanced tumor stage and invasion, poor differentiation, lymph node metastasis, and unfavorable prognosis in patients." (PMID 33362854, 2020). "In this study, we investigated NETO2 expression in breast, prostate, and colorectal cancer using quantitative PCR (qPCR), as well as the effect of shRNA-mediated NETO2 silencing on transcriptome changes in colorectal cancer cells." (PMID 33362854, 2020). "LncRNAs found in our study can also be potential regulators of NETO2 expression in colorectal cancer." (PMID 33362854, 2020). "For colorectal cancer, we expanded a set of samples from a previous study and confirmed that NETO2 expression was increased in about one-third of these tumors (41 and 35% in previous and current studies, respectively)." (PMID 33362854, 2020). "Collectively, our findings demonstrate the deregulation of NETO2 in the breast, prostate, and colorectal cancer and its participation in the tumor development primarily through cellular signaling." (PMID 33362854, 2020). "In colorectal cancer, NETO2 mRNA levels were increased in 35% (2–14-fold) of investigated samples and decreased in 26% of cases (2–28-fold)." (PMID 33362854, 2020). "Although a wide range of studies has proposed increased NETO2 expression in several tumors, we revealed its deregulation in breast, prostate, and colorectal cancers (both decreased and increased mRNA levels)." (PMID 33362854, 2020). "In this study, we analyzed NETO2 expression in prostate, breast, and colorectal cancer samples obtained from Russian patients." (PMID 33362854, 2020). "Increasing evidence showed that NETO2 was an oncogene in colorectal carcinoma and hepatocellular carcinoma." (PMID 29108269, 2017). "Another study pointed out that up-regulation of NETO2 expression correlated with tumor progression and poor prognosis in colorectal carcinoma." (PMID 29108269, 2017). "Furthermore, we performed a correlation analysis between several clinicopathological characteristics of tumors (stage for all cancers, differentiation for prostate and colorectal cancer, mutation, and MSI status for colorectal cancer) and NETO2 expression." (PMID 33362854, 2020). "The upregulation of NETO2 promotes colorectal carcinoma progression and predicts poor prognosis." (PMID 33006432, 2020). "The highest correlation coefficients were observed between NETO2 expression and pathological stage for breast cancer (rs = 0.15) and prostate cancer (rs = 0.25), tumor differentiation for prostate cancer (rs = −0.16), and BRAF mutation status (rs = 0.18) for colorectal cancer." (PMID 33362854, 2020). "Neuropilin and tolloid-like 2 (NETO2), a member of the subfamily containing CUB and LDLa domains, has recently been reported to be upregulated in different types of solid tumors, such as colorectal cancer, pancreatic cancer, and hepatocellular carcinoma." (PMID 34540835, 2021). "Neuropilin and tolloid-like 2 (NETO2) has been found to be overexpressed in different human cancers, but its expression pattern and clinical relevance in colorectal carcinoma (CRC) remains unknown." (PMID 26699544, 2015).
gastric cancer (5 papers, 2019 to 2021). A primary or metastatic malignant neoplasm involving the stomach. "A recent study of gastric cancer has demonstrated that NETO2 is a vital oncoprotein that activates the PI3K/Akt/NF-κB/Snail axis to contribute to gastric carcinoma invasion and metastasis by inducing EMT." (PMID 34540835, 2021). "NETO2 was found closely combined with clinicopathological features and promoted metastasis in gastric cancer." (PMID 33390848, 2021). "NETO2 drives metastasis in gastric cancer by activating PI3K/Akt/NF‐κB/Snail axis." (PMID 33006432, 2020). "However, the expression pattern and clinical relevance of NETO2 in gastric cancer (GC) remain to be elucidated." (PMID 30770791, 2019).
lung carcinoma (5 papers, 2015 to 2024). "NETO2 was reported to be overexpressed in several cancers, including renal cancer, lung cancer and colon cancer." (PMID 32649057, 2020). "Our research group was one of the first to reveal NETO2 overexpression in solid tumors (renal and lung cancer)." (PMID 33362854, 2020). "LSR may also activate the SARS−CoV−2 S proteins and increase the viral infection of lung cancer cells, along with host co-receptors that might be involved in cell infection, such as NETO2, GRP87, and transmembrane protease serine 4 (TMPRSS4)." (PMID 39228892, 2024). "Notably, we previously demonstrated that NETO2 mRNA level is frequently overexpressed in kidney and lung cancers, and resultantly suggested it as a potential marker to early diagnosis of these diseases." (PMID 29297384, 2017).
prostate carcinoma (5 papers, 2019 to 2025). A carcinoma that arises from epithelial cells of the prostate gland. "In case of prostate cancers, NETO2 expression has been found to be closely associated with tumour heterogeneity which is related to therapeutic response, chemotherapy resistance and the consequent risk of poor outcome." (PMID 32638511, 2020). "Recent studies have highlighted the role of the NETO2 gene in many types of cancer, including prostate cancer (PCa), demonstrating its potential in predicting recurrence." (PMID 40034593, 2025). "NETO2 expression was characterized by a 2–33-fold average increase in 40% of prostate cancer samples and a 2–7-fold average decrease in 22.5% of cases." (PMID 33362854, 2020). "Negligible correlations were observed between the NETO2 expression and stage of breast and prostate cancer, as well as differentiation of prostate tumors." (PMID 33362854, 2020). "In this study, we first demonstrated the deregulation of NETO2 expression in breast and prostate cancer." (PMID 33362854, 2020). "In prostate cancer, the expression level of NETO2 was significantly correlated with intratumor heterogeneity in association with PTEN deletion." (PMID 30770791, 2019). "In prostate cancer, NETO2 mRNA levels were upregulated in 40% of cases, with a 1.8 median change." (PMID 33362854, 2020). "The results from this study emphasize the importance of incorporating NETO2, HPN, AR, and KLK3 as part of a comprehensive model for prostate cancer prognosis, pointing towards their potential to improve clinical outcomes." (PMID 40034593, 2025).
glioma (4 papers, 2019 to 2023). A benign or malignant brain and spinal cord tumor that arises from glial cells (astrocytes, oligodendrocytes, ependymal cells). "Bioluminescence imaging showed that compared with blank or His-NETO2-Del1 group, TAMs with His-NETO2-FL recovered the effects of sLRIG3 inhibiting glioma growth." (PMID 36639372, 2023). "Notably, bioluminescent imaging showed that silencing NETO2 promoted glioma growth, and immunohistochemical analysis confirmed that NETO2 was significantly downregulated in glioma allografts co-implanting GL261-LRIG3 and TAM-shNETO2." (PMID 36639372, 2023).
breast carcinoma (3 papers, 2019 to 2023). "The NETO2 mRNA level was predominantly downregulated in breast cancer (44%), with elevated gene expression observed in 31% of samples." (PMID 33362854, 2020). "In breast cancer, NETO2 gene expression was increased in 31% of cases (2–24-fold), with decreased mRNA levels detected in 44% of samples (2–18-fold)." (PMID 33362854, 2020).
cervical carcinoma (3 papers, 2015 to 2017). A carcinoma arising from either the exocervical squamous epithelium or the endocervical glandular epithelium. "Initially, NETO2 was believed to be a brain-specific protein; however, recent studies described overexpression of NETO2 in several types of cancer, including renal, lung, colon, and cervical carcinomas." (PMID 29297384, 2017). "A research showed that the NETO2 mRNA level was increased in 50% of cervical cancer samples." (PMID 29312619, 2017).
hepatocellular carcinoma (3 papers, 2017 to 2021). A malignant tumor that arises from hepatocytes. "A five‐gene hepatic signature including NETO2 may play a feasible role in the prediction of tumour growth and risk of death in patients with hepatocellular carcinoma (HCC), suggesting a useful molecular tool for therapeutic management of HCC patients." (PMID 32638511, 2020).
esophageal cancer (2 papers, 2020 to 2021). A primary or metastatic malignant neoplasm involving the esophagus. "Among TCGA database, esophageal carcinoma is one of the highest expression level of NETO2." (PMID 33390848, 2021). "Notably, regulation of NETO2 expression with microRNAs and microRNA-lncRNA interaction has been recently shown in esophageal cancer." (PMID 33362854, 2020).
glioblastoma (2 papers, 2022 to 2023). The most malignant astrocytic tumor (WHO grade IV). "This study suggests that sLRIG3, modulated by ADAM17 in GBM tumor cells, interacts with the CUB1 domain of NETO2 and plays a key role in attenuating the tilt towards an M2-dominant TAM population, thus remodelling the heterogeneous glioblastoma microenvironment, and suppressing GBM malignant growth." (PMID 36639372, 2023).
hemangioma (2 papers, 2015 to 2017). A benign vascular lesion characterized by the formation of capillary-sized or cavernous vascular channels. "NETO2 expression was reported to be upregulated in proliferating pediatric hemangiomas." (PMID 29297384, 2017).
lymph node metastasis (2 papers, 2019 to 2021). "Our clinicopathologic association findings revealed that higher levels of NETO2 were associated with lymph node metastasis." (PMID 33390848, 2021). "Moreover, the expression of NETO2 was positively correlated with clinical stage, invasion depth, lymph node metastasis, and tumor size, but inversely correlated with overall and disease-free survival rates." (PMID 30770791, 2019). "The protein level of NETO2 was markedly correlated with TNM stage (p = 0.004), tumor invasion depth (p = 0.016), lymph node metastasis (p = 0.022), and tumor size (p = 0.045)." (PMID 30770791, 2019).
osteosarcoma (2 papers, 2014 to 2024). A usually aggressive malignant bone-forming mesenchymal neoplasm, predominantly affecting adolescents and young adults. "NETO2 can act as an oncogene for osteosarcoma by activating the PI3K/AKT pathway." (PMID 38240704, 2024).
prostate tumors (2 papers, 2020 to 2021). "Compared to normal tissues, ARHGEF38, NETO2, GOLM1, and SAPCD2 were hypomethylated in prostate tumors, while PRSS21 was hypermethylated in prostate tumors compared, which may be the underlying mechanism for the abnormal expression of the five genes in PCa." (PMID 34540835, 2021).
renal carcinoma (2 papers, 2020 to 2022). A carcinoma arising from the epithelium of the renal parenchyma or the renal pelvis. "In contrast, high expression of FRZB, MYBL2, MYL2, NETO2, PLSCR4, and TES predicts an unfavorable outcome in endometrial, head and neck, liver, pancreatic, and renal cancer." (PMID 36497479, 2022).
viral infection (2 papers, 2024 to 2025). "Finally, signaling molecules such as WNT5A, MET, and NETO2 are modulated by bacterial and viral infections (including SARS-CoV-2 and M. tuberculosis) to alter cell survival, inflammation, and proliferation pathways, reinforcing the pathogenic role of these exosome-borne receptors." (PMID 41440381, 2025). "NETO2 and lipolysis-stimulated lipoprotein receptor (LSR) may also activate SARS-CoV-2 S proteins and increase the viral infection of LC cells, while LSR is related to Clostridium difficile cell binding, to regulate cell proliferation, invasion, and migration via MAPK signaling." (PMID 41440381, 2025).
kidney cancer (1 paper, 2021). Primary or metastatic malignant neoplasm involving the kidney. "Studies with SAP30 gene have shown its relationship with histone deacetylase process in eukaryotes that induces Sin3, the histone deacetylases HDAC1 and HDAC2, and acting as a transcription factor for NETO2 gene in kidney cancer." (PMID 34646299, 2021).
psoriasis (1 paper, 2019). An autoimmune condition characterized by red, well-delineated plaques with silvery scales that are usually on the extensor surfaces and scalp. "We observed the upregulation of CMKLR-1, COL8A-1, NETO-2, NRK, SYTL-2, and SULF-2 in dermal mesenchymal stem cells derived from patients with psoriasis at both mRNA and protein level, however, a significant downregulation of SFRP-2 between two groups." (PMID 30760317, 2019).
sarcoma (1 paper, 2024). A usually aggressive malignant neoplasm of the soft tissue or bone. "Finally, a prognostic model for sarcoma patients was constructed using six hub genes: risk score = 0.05 × VEGFA + 0.25 × HMGB3 + 0.22 × FASN + 0.40 × RCC1 + 0.46 × NETO2-0.10 × BIRC5." (PMID 38240704, 2024).
tumor (18 papers, 2014 to 2025). "Here, our study found that NETO2 expression in ESCC patients was associated with tumor clinical stage and lymph node metastasis status." (PMID 33390848, 2021). "Recently, it has been reported that elevated NETO2 expression was associated with tumor progression, poor prognosis, and reduced survival in cancer patients." (PMID 33362854, 2020). "Recent studies have shown that NETO2, which is primarily implicated in neuron‐related processes, is expressed in diverse human tumour types." (PMID 32638511, 2020). "sLRIG3 may play an intricate role in GBM TME, while NETO2 might cause an opposite tumor biological effect through different mechanisms in various malignant tumors." (PMID 36639372, 2023). "In the present study, we hypothesized that the association of NETO2 overexpression with tumor progression, invasion, and metastasis may be indicative of its involvement in the epithelial-mesenchymal transition in CRC." (PMID 29297384, 2017). "Preoperative serum PSA levels, tumor staging, and Gleason score, and also including the NETO2 gene, remained consistent for all six predictor groups, underscoring their primal role in classification." (PMID 40034593, 2025). "Knocking down NETO2 by shRNA or knocking out NETO2 by CRISPR can block the interaction of sLRIG3 and NETO2, thus largely abrogating the tumor-suppressive effects of sLRIG3." (PMID 36639372, 2023). "It is crucial to further identify the detailed targets of interaction between sLRIG3 and NETO2 and how they exert their tumor-suppressive effects in GBM TME." (PMID 36639372, 2023). "Gain-of-function and loss-of-function analyses showed that NETO2 stimulated ESCC cell proliferation while suppressing apoptosis in vitro and enhanced tumor growth in vivo." (PMID 33390848, 2021). "NETO2 overexpression was associated with ESCC Histological grade (P=0.005), TNM stage (P=0.003), Tumor size (P=0.024), depth of invasion (P<0.01) and lymph node metastasis (P=0.007) but we did not observe difference with patient's age and sex." (PMID 33390848, 2021). "A recent study found that NETO2 plays an important role in tumor progression in pancreatic and nasopharyngeal carcinomas 14,15." (PMID 33390848, 2021). "NETO2 was determined as a target of miR-206 and miR-143-5p, and participation of NETO2 tumor progression and angiogenesis through overexpression of lncRNA FAM225A absorbed miR-206 was revealed." (PMID 33362854, 2020). "NETO2 expression was examined in 220 GC samples and paired adjacent non-tumor tissues by immunohistochemistry (IHC)." (PMID 30770791, 2019). "High expression of NETO2 (NETO2high) was more frequent in GC tissues (128/220, 58.18%) compared with adjacent non-tumor tissues (82/220, 37.27%) (p < 0.001)." (PMID 30770791, 2019). "Survival analyses based on tumor stage (early and advanced) demonstrated that high expression of NETO2 significantly predicted poor DSS in patients with early stage tumors (p = 0.027)." (PMID 26699544, 2015). "The independent prognostic significance of NETO2 expression on CRC-specific survival based on tumor stage was further evaluated with a Cox regression model." (PMID 26699544, 2015). "NETO2 has been found to be aberrantly expressed in various malignant tumors, but the specific mechanism of NETO2 in tumor progression remains unclear." (PMID 36639372, 2023). "To investigate whether NETO2 can inhibit GBM tumor growth by inhibiting the M2 polarization of TAMs, we knocked down NETO2 in TAMs derived from BMDM and RAW264.7 cell line." (PMID 36639372, 2023). "In conclusion, our study found that both sLRIG3 and NETO2 may affect tumor progression through multiple pathways." (PMID 36639372, 2023). "Additionally, to further investigate the role of NETO2 in tumor progression, we established ECA109 cell lines with specific NETO2 shRNA stably downregulating NETO2." (PMID 33390848, 2021).